TRIM17 (tripartite motif containing 17)
Diseases named in the same sentence as TRIM17 in open-access papers (continued):
Sharing a sentence is not in itself a finding about the gene and the disease.
Parkinson disease (2 papers, 2021 to 2025). A progressive degenerative disorder of the central nervous system characterized by loss of dopamine producing neurons in the substantia nigra and the presence of Lewy bodies in the substantia nigra and locus coeruleus. "TRIM17 is potentially implicated in the pathogenesis of Parkinson’s disease in several ways." (PMID 34069831, 2021). "This duality of action confers several pivotal roles to TRIM17 in crucial cellular processes such as apoptosis, autophagy or cell division, but also in pathological conditions as diverse as Parkinson’s disease or cancer." (PMID 34069831, 2021). "Consistent with stress-induced expression of TRIM17, the mRNA level of Trim17 is increased in the midbrain of mice treated with the neurotoxin MPTP (1-methyl-4-phenyl-1,2,3,6-tetrahydropyridine), a largely used animal model of Parkinson’s disease." (PMID 34069831, 2021).
lung carcinoma (1 paper, 2025). "TRIM17 is upregulated in cisplatin-resistant lung cancer tissues and cells and reduces cisplatin sensitivity of lung cancer cells by promoting ubiquitination and degradation of RBM38 protein." (PMID 41145484, 2025).
neuroblastoma (1 paper, 2015). Neuroblastoma (NB) is the most common solid, extracranial childhood tumor. "It has been proposed that DEHP might impair fetal brain development through activation of Trim17 protein via PPARγ (peroxisome proliferator-activated receptor-γ) leading to apoptosis based on an in vitro study of neuroblastoma cells." (PMID 25280125, 2015).
cancer (12 papers, 2009 to 2025). A tumor composed of atypical neoplastic, often pleomorphic cells that invade other tissues. "However, existing data clearly indicate that the role TRIM17 can have in cancer depends on tumor types, the mechanisms underlying transformation and resistance, and the nature of the proteins that it can target in these pathways." (PMID 34069831, 2021). "It is suggested that TRIM17 may exert a pro-cancer effect by targeting different substrates in different tumors." (PMID 41145484, 2025). "Notably, PTPN1, TRIM46, TRIM17, FCGR1A, IRF5, IRF6, and CAMK2B had a higher frequency of gain mutations in most human cancer types." (PMID 37941546, 2023). "This is of particular importance, as the specific interaction with its substrates or its TRIM partners may be targeted in pathological conditions in which TRIM17 is induced, for the treatment of human diseases as diverse as PD and cancers." (PMID 34069831, 2021). "Although many studies are necessary to establish the pathological role of TRIM17 in neurological diseases, cancer or other disorders, its implication in cellular processes that are dysregulated in many pathologies, such as cell death and proliferation, makes it an obvious candidate." (PMID 34069831, 2021). "Indeed, we have previously shown that TRIM17 is expressed at very low levels in most conditions but is transcriptionally induced at a very high level following a cellular stress such as trophic factor deprivation or anti-cancer drugs." (PMID 40379611, 2025). "Interestingly, an independent study aiming at elucidating the molecular basis of immune resistance in cancer cells showed that NANOG-mediated/HDAC1-driven epigenetic silencing of TRIM17 resulted in stabilization of MCL1 and subsequent resistance to apoptosis in immune-edited tumor cells." (PMID 34069831, 2021). "E3 ubiquitin ligases (Mule, SCFβ-TrCP, SCFFBW7, TRIM17, APC/CCdc20, and FBXO4) and deubiquitinases (USP9X, Ku70, USP13, JOSD1, and DUB3) work together to balance MCL1 stability, which has an important role in the chemoresistance of cancer cells." (PMID 33803505, 2021).
tumor (8 papers, 2015 to 2025). "TRIM17 plays a tumor-promoting role by promoting ubiquitination and degradation of BAX protein and inhibiting cell apoptosis." (PMID 41145484, 2025). "Several genome-wide KO screens by CRISPR/Cas9 have identified TRIM17 as one of the genes whose inactivation results in drugs resistance in tumor cell lines." (PMID 34069831, 2021). "Subsequently, we investigated whether TRIM17 influences tumor progression by modulating FTO protein expression and regulating the AKT/mTOR signaling pathway." (PMID 41145484, 2025). "Limited literature has confirmed that TRIM17 plays an important role in tumor progression." (PMID 41145484, 2025). "Furthermore, knockdown of TRIM17 in AGS cells suppressed tumor growth in a xenograft mouse model." (PMID 39768197, 2024). "However, only β-TrCP, FBW7, and TRIM17 are reduced in the non-tumor adjacent tissue." (PMID 37259388, 2023). "The correlation analyses between the 8 TRIM molecules and TMB (tumor mutational burden)/MSI (microsatellite instability)/ICMs discovered that as the expression level of TRIM5/21/22/24/28/34/47 increased, the TMB score also increased significantly, while TRIM17 showed an opposite outcome." (PMID 37367937, 2023). "Overexpression of TRIM17 in AGS and HGC-27 cells enhanced the proliferation and survival of tumor cells, whereas its suppression resulted in increased apoptosis." (PMID 39768197, 2024). "However, the mechanisms by which TRIM17 confers drug sensitivity in these tumor cells has not been addressed." (PMID 34069831, 2021).
TRIM17 also shares sentences with these, for which no sentence is quoted: lung adenocarcinoma (2 papers); bladder urothelial carcinoma (1); breast invasive carcinomas (1); cholangiocarcinoma (1); esophageal carcinoma (1); genetic diseases (1); glioblastoma (1); HIV-1 infection (1); infection (1); kidney chromophobe (1); lung squamous cell carcinoma (1); non-small cell lung carcinoma (1); prostate adenocarcinoma (1); rectum adenocarcinoma (1); stomach adenocarcinoma (1); thyroid carcinoma (1); triple-negative breast carcinoma (1); tuberculosis (1); uterine corpus endometrial carcinoma (1).